BMP7 (bone morphogenetic protein 7)
Diseases named in the same sentence as BMP7 in open-access papers (continued):
Sharing a sentence is not in itself a finding about the gene and the disease.
Obesity (23 papers, 2007 to 2026). Accumulation of substantial excess body fat. "The parameters predisposing some patients to BMP7-aAB are probably similar to those determining the risk of autoimmunity in the general population, including genetic predisposition, obesity, smoking status, and other environmental factors." (PMID 27617228, 2016). "From the 23 known genes and 13 Riken transcripts; Dok5, Mc3r, Bmp7, and Pck1 have been associated with obesity." (PMID 25613955, 2015). "BMP7 may be a promising tool for the treatment for obesity and associated comorbidities." (PMID 34258293, 2021). "Together, these data show that BMP7-mediated recruitment and activation of BAT only occurs at subthermoneutral temperature, and is thus likely dependent on sympathetic activation of BAT, and that BMP7 may be a promising tool to combat obesity and associated disorders." (PMID 24066098, 2013). "Localized delivery of smart Bmp7 mRNA was achieved using decorated exosomes for the treatment of obesity." (PMID 38965553, 2024). "Among them, bone morphogenetic protein 7 (BMP7) has been shown to induce adipogenesis and activation of brown and beige fat, thus protecting against diet-induced obesity and insulin resistance." (PMID 39872552, 2023). "Accordingly, BMP-7 has received considerable attention as a potential therapeutic target in the treatment of obesity." (PMID 37239098, 2023). "The autocrine mediator BMP7 led to moderate browning with the upregulation of the classical brown marker Zic1 instead of Tbx1 targets for enhancing thermogenesis in obesity." (PMID 34258293, 2021). "As a proof, the SmartExo@Bmp7 induced local white adipose tissue browning, and it would be a promising strategy for anti-obesity therapy." (PMID 34863187, 2021). "The results showed that SmartExo system was a great prospect of targeting delivering strategy, and its efficiency was proved by targeting delivery of Bmp7 on OAT for obesity treatment." (PMID 34863187, 2021). "Overall, these data are in full accordance with increased fatty acid and carbohydrate oxidation induced by BMP7 treatment and underscore the therapeutic potential of BMP7 to diminish diet-induced obesity and related disorders." (PMID 24066098, 2013). "We aimed to elucidate the role of sympathetic activation in the effect of BMP7 on BAT by treating mice with BMP7 at varying ambient temperature, and assessed the therapeutic potential of BMP7 in combating obesity." (PMID 24066098, 2013). "Loss of BMP7 results in brown fat hypoplasia and reduced UCP1 levels, whereas systemic BMP7 administration increases BAT mass and thermogenic capacity, highlighting its therapeutic potential in obesity." (PMID 41596403, 2026). "Based on data from animal studies or other clinical applications in addition to obesity, adipokines including adiponectin, vaspin, resistin, chemerin, visfatin, bone morphogenetic protein 7 (BMP-7) and tumor necrosis factor alpha (TNF-α) provide potential for human clinical application." (PMID 37239098, 2023). "Interestingly, to further investigate the potential role of BMP-7 as a therapeutic option for obesity, a previous study in mice investigated its role in appetite regulation." (PMID 37239098, 2023). "BMP7 gene therapy counteracts insulin resistance and obesity." (PMID 36339449, 2022). "Therefore, the utilization of BMP7 for the treatment or mitigation of obesity and its co-morbidities, such as T2DM and CVD, is of interest." (PMID 35646839, 2022). "To examine whether BMP7-loaded silk hydrogel could counteract obesity and its sequelae, we fed mice with a high fat diet containing 45 kcal% fat for 3 months." (PMID 35646839, 2022). "Overall, BMPs, mainly including BMP9, BMP4, BMP2, and BMP7, may exert functions both in bone and in obesity as well as glucose metabolism." (PMID 34258293, 2021). "This newly smart exosome-based delivering strategy of Bmp7 could provide new directions in the development of therapeutics for obesity." (PMID 34863187, 2021).
Obesity (continued). "Furthermore, BMP7 was shown to reverse obesity phenotype by regulating appetite through the central mTOR pathway in the brain." (PMID 31831718, 2019). "We anticipate that BAT may be a promising novel treatment goal, and BMP7 a treatment modality, in fighting obesity and related disorders." (PMID 24066098, 2013). "Furthermore, we found that BMP7 diminishes obesity and liver lipid accumulation, and attenuates dyslipidemia and hyperglycemia in diet-induced obese mice." (PMID 24066098, 2013). "Moreover, BMP7 was able to diminish white fat content, liver lipid accumulation as well as to reduce dyslipidemia and hyperglycemia in diet-induced obese mice, underscoring the therapeutic potential of BMP7 in combating obesity and related disorders." (PMID 24066098, 2013). "BMP4 is widely acknowledged as a protein that facilitates the differentiation of white adipocytes, whereas BMP7 has emerged as a specific regulator of brown adipogenesis, suggesting that targeting BMP7 could represent a potential therapeutic approach for obesity." (PMID 39604763, 2024). "Brain transcriptome analyses in obese mice identified several obesity-related pathways (e.g. leptin, somatostatin, and nemo-like kinase signaling), as well as genes involved in feeding and appetite (e.g. Pmch, Neurotensin) and in metabolism (e.g. Bmp4, Bmp7, Ptger1, Cox7a1)." (PMID 25629159, 2015). "The study results revealed that localized US-assisted delivery of Bmp7 elicited efficient browning of OAT and proved as a promising anti-obesity therapy." (PMID 38965553, 2024). "BMP2, BMP4, BMP6, BMP7, and BMP9 have been shown to affect the pathophysiological process of obesity and glucose metabolism beyond bone metabolism." (PMID 34258293, 2021). "Although the function of BMP7 in energy metabolism is not well characterized, it seems to act through leptin-independent mechanisms, making it of therapeutic interest in obesity, since the obese state is often characterized by leptin resistance." (PMID 39033139, 2024). "As we noticed, most of the anti-obesity gene therapy approaches exploit the possibility of inducing white-to-beige adipose transition by overexpressing the genes coding for secreted factors, such as leptin, FGF21, or BMP7." (PMID 38931457, 2024). "Taken together, AJLE showed anti-obesity properties, including adipogenesis inhibitory effects through the PPARγ-C/EBPs pathway and brown adipocyte induction effect by increasing UCP-1, PRAM16, and BMP7 expression." (PMID 37511251, 2023). "As a proof-of-concept study, we confirmed that smart exosome-based system could deliver Bmp7 locally and induce the local omental adipose tissue (OAT) browning efficiently, serving as a promising strategy for anti-obesity therapy." (PMID 34863187, 2021). "The obesity mice were randomly allocated to PBS, Exo, Exo@Bmp7 or SmartExo@Bmp7 treatment group." (PMID 34863187, 2021). "Interestingly, intra-cerebroventricular administration of BMP7 was shown to ameliorate the HFD-associated metabolic complications, suggesting that BMP7 may be explored as an attractive obesity therapeutic for diet-induced obesity and leptin-resistant conditions.." (PMID 31831718, 2019). "Therefore, the aim of the present study was to elucidate the role of ambient temperature, which determines the sympathetic output to BAT, in the effect of BMP7 on BAT and to asses the therapeutic potential of BMP7 in combating obesity and related disorders." (PMID 24066098, 2013). "Together, our results show that low subthermoneutral ambient temperature, at which sympathetic activation is present, is required for BMP7-mediated recruitment and activation of BAT and suggest that BMP7 may be a therapeutic tool to ameliorate obesity, and related disorders." (PMID 24066098, 2013). "Moreover, the role of sympathetic activation in the effects of BMP7 on brown fat function and energy metabolism, and the therapeutic potential of BMP7 to treat dyslipidemia and obesity has not been reported yet." (PMID 24066098, 2013).
Obesity (continued). "In addition, further studies are needed to determine if silk-mediated BMP7 delivery is sufficient to prevent, as well as reverse, diet-induced obesity and to determine whether or not there are any potential long-term side effects." (PMID 35646839, 2022).
melanoma (22 papers, 2009 to 2024). A malignant, usually aggressive tumor composed of atypical, neoplastic melanocytes. "BMP7 expression was found to be associated with tumor progression and the occurrence of metastasis in malignant melanomas and in colonic carcinoma." (PMID 24069261, 2013). "Induction of EMT by BMP-7 has also been described in other cancer cells, i.e., PC-3 PCa cells, B16 mouse and A2058 human melanoma cells, and in normal airway epithelial cells during restitution of an injured epithelium." (PMID 39682758, 2024). "In recent years, BMP7 was also shown to be involved in regulating the production of melanin and was strongly expressed in metastatic and primary melanoma." (PMID 35372349, 2022). "Hyaluronidase pre-treatment reduced Id1/3 protein expression in response to BMP4 and BMP7 in both melanoma cell lines by around 50%." (PMID 30297743, 2018). "This is in line with constitutive expression of BMPs in human melanoma cell lines and primary melanomas and increased BMP-7 expression in melanomas and their metastases, when compared to nevi." (PMID 29716947, 2018). "The bone morphogenetic protein 7 (BMP7) is a potential metastasis inhibitor that disrupts EMT through Twist-1 inhibition in melanoma WM-266-4 and HEK293T cell lines." (PMID 26425122, 2015). "The most significant SNP on GGA20 was located nearest to bone morphogenetic protein 7 (BMP7), which can effect melanocyte growth and melanoma cell metastasis, and therefore BMP7 was also chosen as one of the most important positional candidate genes for HVP." (PMID 23679099, 2013). "In contrast elevated BMP7 levels correlate with shorter tumour recurrence in malignant melanoma and increased BMP7 levels in colorectal cancer correlates with depth of tumour invasion, liver metastasis, advanced Duke's classification and poor prognosis." (PMID 19298647, 2009). "In the context of malignant melanoma, BMP7 expression correlates with poor prognosis." (PMID 30297743, 2018). "We also determined the effect of BMP4 and BMP7 on proliferation of the melanoma cells." (PMID 30297743, 2018). "In addition, we were able to accentuate that treatment of normal melanocytes with recombinant CTGF caused an increase in BMP7 expression, whereas knocking down CTGF expression via a specific siRNA led to diminished BMP7 expression levels in melanoma cells." (PMID 21673687, 2011). "Moreover, we and others were able to determine Bone Morphogenetic Protein 4 (BMP4), BMP7 and TGFβ as important modulators of melanoma initiation and progression." (PMID 21673687, 2011). "However, evidence indicates that BMP7 is upregulated in the development of melanoma." (PMID 23679099, 2013). "BMP7 could inhibit normal melanocyte growth and tumor growth of human uveal melanomas, and could inhibit metastasis by inducing mesenchymal-to-epithelial transition in melanoma cells." (PMID 23679099, 2013). "In addition, BMP-7 decreased resistance to cisplatin in melanoma cell lines." (PMID 24281103, 2010). "Five genes (CXCL10, TNF, PIK3CD, PIK3R2, and CXCL1) of the TNF signalling pathway and seven genes (CXCL9, GDF15, BMP7, TNFRSF15, CXCL10, TNF, and CXCL1) of the cytokine–cytokine receptor pathway were commonly upregulated in melanoma cells." (PMID 39496484, 2024). "Due to the MET promoting and invasion inhibiting ability of BMP7 or ALK2, BMP7/ALK2 signaling has the potential to act as a metastasis inhibitor, i.e., in human melanoma cells." (PMID 36289908, 2022). "BMP7 acting via ALK2 and SMAD1/5 has been shown to induce the MET in melanoma cells and inhibit metastasis." (PMID 36289908, 2022). "Clinical reports have also indicated that a high-expression level of BMP-7 may serve as a biomarker for metastasis and poor prognosis in various malignancies, such as esophageal cancer, lung cancer, gastric cancer, colorectal cancer, liver cancer, and melanoma." (PMID 25390068, 2014).
melanoma (continued). "Connective tissue growth factor in turn controls expression of BMP7 and the TGFβ pseudo-receptor BAMBI and contributes to tumour progression by increasing migratory and invasive potential of melanoma cells." (PMID 21673687, 2011). "To analyse a potential regulation of CTGF gene expression by BMPs, we incubated Mel Im melanoma cells with recombinant BMP4, BMP7 or the BMP inhibitors noggin and chordin, respectively." (PMID 21673687, 2011). "Bone morphogenetic protein 7 (BMP7) belongs to the transforming growth factor β (TGF-β) family, which not only induces cartilage and bone formation, but also regulates eye development and melanoma tumorigenesis in mammals." (PMID 35372349, 2022). "In addition to driving neural crest migration in the zebrafish embryo, the agonists BMP-2, BMP-7 and nodal induce EMT/invasion in radial growth phase melanoma cells and in human melanocytes in skin reconstructs." (PMID 29716947, 2018). "As TGFβ1, BMP4 and BMP7 are upregulated in melanoma, we were interested whether CTGF expression in the melanoma cells is mediated by these cytokines." (PMID 21673687, 2011). "This pro-EMT effect was quite surprising, as BMP-7 has been identified previously as a MET-inducing (and thus anti-EMT) factor in a range of different cell types, such as alveolar type II cells, adult renal epithelial tubular cells and fibroblasts, hepatic stellate cells, and melanoma cells." (PMID 39682758, 2024). "Furthermore, BMP7 expression correlated with tumor progression, as aggressive melanomas expressed abundant BMP7 mRNA, but primary melanomas did not." (PMID 23049692, 2012). "Moreover, bone morphogenetic protein-7 (BMP-7), a member of the TGF-β superfamily of growth and differentiation factors, has been reported to be able to induce MET in adult renal fibroblasts of the injured kidney, hepatic stellate cells, and melanoma cells, generating functional epithelial cells." (PMID 39682758, 2024). "We found that the CTGF overexpression is not induced by members of the TGFβ superfamiliy and its regulators in melanoma cell lines: Neither TGFβ1, BMP4 nor BMP7 have a significant effect on the CTGF expression." (PMID 21673687, 2011).
osteoarthritis (20 papers, 2006 to 2025). A noninflammatory degenerative joint disease occurring chiefly in older persons, characterized by degeneration of the articular cartilage, hypertrophy of bone at the margins and changes in the synovial membrane. "Secondly, in osteoarthritis patients with Th17-induced inflammation resulting from exposure to metal debris originating from worn cobalt prosthetic joints, BMP-7 was illustrated to suppress the Th17 response and associated inflammation." (PMID 37626268, 2023). "Of relevance to the current topic, these beneficial anabolic outcomes is thought to result from BMP-7 antagonism of TGF-β, as TGF-β is implicated as major driver of catabolism in the progression of osteoarthritis." (PMID 37626268, 2023). "BMP-7 mRNA and protein are also expressed at low levels in articular cartilage of elderly subjects with osteoarthritis owing to methylation of the BMP-7 promoter." (PMID 33019579, 2020). "In a rabbit model of osteoarthritis, Hayashi and colleagues have shown that the intraarticular injection of BMP7 inhibited the progression of OA in a rabbit ACL transaction model of knee OA." (PMID 32722615, 2020). "In this rabbit ACLT model, we examined the optimal dose of BMP-7 for the prevention of osteoarthritis progression." (PMID 18826579, 2008). "Matched pair analyses revealed that weekly 500 ng BMP-7 injections slowed the progression of osteoarthritis." (PMID 18826579, 2008). "The OARSI osteoarthritis scores for histologic analysis were similar in all four groups at 4 and 8 weeks; however, they were significantly better in the 500 ng and 5,000 ng BMP-7 groups than in the control group at 12 weeks." (PMID 18826579, 2008). "In our second series of experiments, we wished to address the inter-animal variability observed in the first study and to investigate the effect of BMP-7 on osteoarthritis progression in a stricter manner." (PMID 18826579, 2008). "A recent study demonstrated that continuous intra-articular infusion of BMP-7 had a protective effect on cartilage degeneration, which suggests the possible utility of BMP-7 as a treatment for human osteoarthritis." (PMID 18826579, 2008). "We investigated the ability of a weekly intra-articular injection of bone morphogenetic protein (BMP)-7 to prevent osteoarthritis in rabbits with anterior cruciate ligament transections." (PMID 18826579, 2008). "The OARSI osteoarthritis score was better at the BMP-7 side than at the contralateral control side in each rabbit at 12 weeks." (PMID 18826579, 2008). "In all animals, the macroscopic osteoarthritis score was better in the BMP-7 injected knee than in the contralateral control knee." (PMID 18826579, 2008). "Indeed, similarly to what was previously found for the osteoarthritis‐derived human chondrocytes (HACs), the supplementation with TGFβ3 and BMP7 combined dramatically improved ATDC5 chondrogenesis." (PMID 40415244, 2025). "Additionally, the potential role of OCN in osteoarthritis, given the established protective effects of BMP7 on cartilage, warrants investigation." (PMID 39337434, 2024). "Bmp7, in turn, prevents the progression of cartilage damage in a rabbit model of osteoarthritis." (PMID 34502478, 2021). "The objective of this research was to investigate the endogenous BMP7 expression in human osteoarthritis (OA) cartilage and the effect of oxygen tension on the single or combined treatment with TGF-β3 and BMP7 on OA chondrocyte redifferentiation in three dimensional (3D) pellet cultures." (PMID 29980690, 2018). "Weekly intra-articular injections of BMP-7 inhibited progression of osteoarthritis." (PMID 18826579, 2008). "Weekly intra-articular injections of BMP-7 inhibited osteoarthritis progression." (PMID 18826579, 2008). "We speculated that periodic knee injections of a small amount of BMP-7 would suppress the loss of cartilage matrix and consequently prevent osteoarthritis progression, without any adverse drug effects." (PMID 18826579, 2008).
osteoarthritis (continued). "Therefore, we further believe that the delayed endochondral ossification observed in OCNem mice attributed to increased chondrocyte differentiation and cartilage formation may serve as a potential regulatory and drug target for osteoarthritis through the BMP7 pathway." (PMID 39337434, 2024). "Furthermore, the expression of BMP-6 and BMP-7 was also decreased in articular cartilage of TNF-transgenic mice, suggesting that loss of BMP expression could be also involved in chronic inflammatory and not only degenerative joint diseases." (PMID 16542506, 2006). "We identified that PPARA, BMP7, IL1B, LEP, ITGA5 and SREBP1 protein levels in osteoarthritic chondrocytes were highly correlated with BMI, suggesting the potential role of metabolic-related proteins in the development of osteoarthritis." (PMID 19011694, 2008). "The overall results suggest that weekly intra-articular injection of a small amount of BMP-7 is a promising nonsurgical treatment for osteoarthritis, and that BMP-7 is an interesting candidate structure/disease-modifying osteoarthritis drug." (PMID 18826579, 2008). "Additionally, bone morphogenetic protein 7 (BMP-7), a potent bone-inducing agent, has been shown to stimulate proteoglycan, collagen, and HA synthesis in cartilage, while vitamin D has been shown to reduce the progression of osteoarthritis." (PMID 22745906, 2012).